FH (fumarate hydratase)
Diseases named in the same sentence as FH in open-access papers (continued):
Sharing a sentence is not in itself a finding about the gene and the disease.
tumor (continued). "However, increasing intrinsic fumarate levels through FH inhibition suppresses CD8+ T cell anti-tumor functions, making FH inhibitors unsuitable for exploring anti-tumor efficacy." (PMID 40370450, 2025). "Despite the clear common change in cell metabolism driven by FH and SDH mutations, FH-mutated VPGL did not display an “SDH-like” molecular phenotype, indicating a different mechanism of tumor development." (PMID 38721148, 2024). "Most cases showed lack of FH staining in tumor cells (62.5%, 10/16), all cases showed retained FH staining in normal kidney tissue." (PMID 38376408, 2024). "Furthermore, depletion of FH and subsequent accumulation of FA can induce EMT, thereby promoting aggressive tumor characteristics." (PMID 38398104, 2024). "Therefore, we constructed a cell line with stable knockdown of FH and PCSK9 using HCT116 cells and established subcutaneous xenograft nude mice to observe their effects on tumor growth." (PMID 38398104, 2024). "Several more enzymes in the TCA cycle, such as succinate dehydrogenase, fumarate hydratase, isocitrate dehydrogenase, SIRT3, etc., also present alterations which directly support the proliferation and survival of tumor cells and are being explored for their anti-cancerous effects." (PMID 37109219, 2023). "Although fumarate itself significantly distinguished FH-MT from FH-WT RCC and its plasma levels correlated with tumor burden, because of its high variability and presence in NC samples, it was insufficiently sensitive to be used as a classifier (with ROCAUC = 0.86)." (PMID 37053010, 2023). "Fumarate hydratase (FH), a mitochondrial enzyme that catalyzes the reversible hydration of fumarate to malate in the tricarboxylic acid (TCA) cycle, has been identified as a bona fide tumor suppressor." (PMID 36269833, 2022). "By using integrative bioinformatics assessment of both the tumour infiltrate (IIL, IIH) and the function of its component cells (FL, FH), we were able to identify 4 different tumour immune microenvironment profiles in our cohort, namely, IIL-FL, IIL-FH, IIH-FL and IIH-FH." (PMID 36253523, 2022). "We then utilized siRNA to knock down the expression of FH in two PDAC cell lines (SW1990 and PANC-1), and further examined tumor cell proliferation, detected the tumor cell glycolytic rates as well as evaluated the concentration of core metabolites of glucose metabolism." (PMID 36434634, 2022). "Tumor metabolomics and detailed immunohistochemistry of SDHB, FH and GLS1 enzymes may provide help in the future." (PMID 34439371, 2021). "The disruption of Krebs cycle enzymes leads to accumulation of the oncometabolites succinate (SDHx), fumarate (FH) or 2-hydroxyglutarate (IDH) that drive tumorigenesis by DNA hypermethylation, inactivation of tumour suppressor genes and HIF alpha stabilisation." (PMID 34834591, 2021). "Immunohistochemical staining with anti-FH antibody (mousemonoclonal, clone J-13, 1:10000, SC-100743, SANTACRUZ, CA, USA) demonstrated no expression of FH in tumor cells." (PMID 31182090, 2019). "Fumarate hydratase (FH) and succinate dehydrogenase (SDH) are tumor suppressors." (PMID 30456204, 2018). "Here, we performed an integrative analysis to investigate at a genome-scale level the regulatory interactions between metabolism and signalling using cell lines derived from an HLRCC tumor, UOK262, and the FH reconstituted counterpart, UOK262pFH, which we previously generated." (PMID 29191787, 2018). "In contrast, controls consisting of DNA isolated from other liver lobes of the same mouse containing transplanted RGB-marked FH-hTERT clusters but no tumor were all negative for this insertion (data not shown)." (PMID 29383183, 2017).
tumor (continued). "FH and 2SC assays were inversely correlated in our uRCC cohort, and they identified four tumours that were positive for 2SC and negative for FH staining." (PMID 27713405, 2016). "The identification of FH as a tumor suppressor was the second description, following the identification of the SDHx genes in hereditary PGL/PCC syndromes, of a gene translated into an intermediary metabolism enzyme also being a tumor-suppressor gene." (PMID 27047799, 2016). "Despite these observations being supportive of a tumor suppressor function, evidence for a direct role of FH in tumorigenesis is lacking." (PMID 23555580, 2013). "Analysis of mRNA levels reveals that over 70% of the tumor samples demonstrated reduced FH mRNA levels relative to normal matched renal parenchyma." (PMID 21695080, 2011). "FH is an enzyme placed in the Krebs cycle immediately behind SDH, suggesting that tumor development may involve similar mechanisms including an important role for succinate accumulation." (PMID 19949549, 2009). "Despite the closely related function of FH and SDH proteins, the tumor spectra in HPGL and HLRCC show little overlap, indicating that although biochemically related, the mitogenic stimulus leading to tumor formation must be cell specific." (PMID 18366737, 2008). "Most have not found any significant difference in tumour size between FH+ and FH− patients, whereas Mohammed observed a trend and Colditz reported a higher percentage of T1 in women FH+ (60%) vs FH− (54%)." (PMID 15162141, 2004). "Fumarate hydratase which is a component of the tricarboxylic acid cycle, acts as a tumour suppressor, its activity being very low or absent in tumours from individuals with leiomyomatosis." (PMID 12177782, 2002). "In addition, Rbm15 knockout significantly exhibited enhanced FH expression in MC38-derived xenograft tumors, demonstrating that RBM15 may regulate anti-tumor immune responses via FH modulation." (PMID 40370450, 2025). "Fumarate hydratase (FH) mutant tumours are a rare non-ccRC subtype with poor prognosis." (PMID 38594593, 2024). "It should be noted that FH immunohistochemistry had not been performed on the tumour sample, which could have oriented the diagnosis for this syndrome." (PMID 38002934, 2023). "Finally, one patient with FH(−) and with BC as the only tumor (diagnosed at 26 years of age) was found to have a non-coding spliceogenic LPV in RAD51C (c.965 + 5G > A)." (PMID 36329109, 2022). "Similarly, the tumor suppressors SDH (succinate dehydrogenase), FH (fumarate hydratase), and IDH (isocitrate dehydrogenase) are responsible for maintaining the tricarboxylic acid (TCA) cycle, while their loss leads to genetic instabilities and epigenetic alterations." (PMID 35208228, 2022). "Furthermore, FH, like SDH, is also regulated by RT-induced miRNA-378 resulting in fumarate accumulation, and might thereby contribute to processes triggering tumor repopulation." (PMID 32799884, 2020). "Another WES study applied to a tumor exhibiting an SDHx-like molecular phenotype (i.e., pseudohypoxic and CIMP profiles) in the absence of SDHx or FH mutations, identified a germline mutation in the SLC25A11 gene, which encodes the mitochondrial α-KG/malate carrier." (PMID 31100940, 2019). "Lack of the functional PTX3 and/or fH might exacerbate pathophysiological consequences during tumor growth and development due to complement dysregulation." (PMID 30619374, 2018). "Although it has been extensively reported that FH deficiency is associated to fumarate-dependent epigenetic deregulation, supporting the notion of FH as a tumor suppressor, the molecular mechanisms by which FH gene expression is controlled is not well clarified." (PMID 28352611, 2017). "Finally, we conclude that the tumor suppressor functions of FH are tissue specific and do not extend to hematopoietic cells." (PMID 28202494, 2017).
tumor (continued). "Although we did not observe tumor formation in the kidneys of the FH+/− KO rats, the anaplastic lesions in the medullary field of the kidney may indicate an early tumor development process, and this finding merits additional studies." (PMID 27556703, 2016). "On the other hand, one tumour (T71) with FH G401V somatic mutation was found to be FH positive/2SC negative, and lacked histologic features of HLRCC or FH-deficient RCC40, 42, suggesting that FH G401V might be better categorized as a passenger mutation." (PMID 27713405, 2016). "FH encodes an enzyme that is part of the mitochondrial tricarboxylic acid (TCA) cycle involved in cellular energy metabolism and appears to function as a tumor suppressor since its activity is very low or absent in tumors from individuals with HLRCC." (PMID 26983443, 2016). "Parallel to the succinate accumulation hypothesis, defects in three other TCA cycle enzymes have been linked to competitive inhibition of α-KG-dependent dioxygenases and tumor formation: isocitrate dehydrogenase (IDH), fumarate hydratase (FH), and malate dehydrogenase 2 (MDH2)." (PMID 26294907, 2015). "Since HIF activation is a direct consequence of inactivation of the FH tumor suppressor, irrespective of hypoxia, this link might indicate causality." (PMID 22014577, 2011). "For Krebs cycle DH, there was a substantial decrease of isocitrate DH (IDH) and α-ketoglutarate DH (OGDH) in contrast to a modest activation of malate DH (MDH) expression, while succinate DH (SDH) and fumarate hydratase (FH) showed no statistically significant changes in expression in tumor tissues." (PMID 19558692, 2009). "For FH-negative mutation fibroids (in ULM7.1, ULM7.2, ULM7.3, ULM7.4 and ULM7.8) observed in this patient, the presence of other genetic mutations such as MED12 are still active in the subset of these fibroids, and the MED12 mutation alone can drive tumour formation." (PMID 37113812, 2023). "Importantly, although less significant than its effect on G6PD, p52-ZER6 might also affect the expression of other glucose metabolism-related genes, such as FH, PKM2, TIGAR, LDHA, GLUT1, and HK2, thereby contributing to tumor metabolic reprogramming through multiple pathways." (PMID 36977688, 2023). "The tumor was histologically composed of oncocytic cells that expressed KRT7, vimentin, SDHA, SDHB and fumarate hydratase, but not KIT, GATA3 and alpha-methylacyl-CoA racemase." (PMID 39980061, 2025). "With the clear recognition of molecularly defined RCC with papillary growth (e.g., FH-deficient RCC), it can be hypothesized that “type 1” and “type 2” tumors may actually represent progression of “true papillary RCCs from lower to higher grade disease” rather than being different tumor types." (PMID 34680535, 2021). "Other alterations were very rare as only one tumor showed HMGA2 overexpression (4%) and none displayed biallelic FH inactivation." (PMID 28592321, 2017). "Additionally, in this case, the tumor cells showed Ki67<5%, and did not express CD117, TFE3, HMB45, or SDHB, while expressing FH and INI1(SMARCB1)." (PMID 41306531, 2025). "The tumour cells were also positive for GATA3, E-cadherin, Pax-8, Succinate dehydrogenase B (SDHB) and Fumarate hydratase (FH), and negative for vimentin, Carbonic anhydrase 9 (CA9), CD10, P504s, CK20, TFE3, TFEB, HMB45, ALK and Forkhead box protein I1 (FOXI1)." (PMID 36816543, 2023). "Human type 2 papillary renal cell carcinoma (PRCC2) cells were cultivated, and the results showed that accumulation of fumarate in cells lacking FH contributed to PTEN inhibition to activate PI3K/AKT signaling, tumor growth in PRCC2, and the development of sunitinib resistance in PRCC2 cells." (PMID 38139831, 2023).
tumor (continued). "All the five tumours in this study had a typical immunophenotype characterized by diffuse positivity for CK7 and negativity for CD117, and were also positive for PAX-8, E-cadherin, FH and SDHB, but negative for vimentin, CD10, P504s, CA9, CK20, TFE3, TFEB, HMB45, and ALK." (PMID 36816543, 2023).
cancer (310 papers, 2002 to 2026). A tumor composed of atypical neoplastic, often pleomorphic cells that invade other tissues. "The ASL reaction is known to be reversible and is a net producer of argininosuccinate in certain conditions such as in fumarate hydratase-deficient cancers, in which the consumption of fumarate by ASL enables survival." (PMID 40454944, 2025). "Despite immune checkpoint inhibitors (ICIs) showing efficacy in other cancers, responses in FH-deficient RCC remain suboptimal." (PMID 41112295, 2025). "In pan-cancer studies, the mean prevalence rates were 0.54% for FH mutations, 7.75% for copy number alteration (CNA) deletions (including shallow and deep deletions), and 5% for 1q arm loss." (PMID 41008787, 2025). "Here they show that HDAC6 inhibition regulates fumarate hydratase (FH), disrupts mitochondria, increases fumarate, and causes cancer cell death." (PMID 40721560, 2025). "Mutations in fumarate hydratase (FH) lead to hereditary as well as sporadic forms of cancer and these malignancies are characterized by fumarate accumulation." (PMID 38922759, 2024). "These compensatory metabolic changes allow cancer cells to continue producing energy even when FH mutated or is inactivated." (PMID 38791507, 2024). "In summary, MIRR4435-2HG is specifically overexpressed in FH-deficient RCC cancer tissues and is closely related to the clinical prognosis." (PMID 38374146, 2024). "We firstly used cellular immunofluorescence to detect the MIR4435-2HG localization and found that MIR4435-2HG was mainly localized in nucleus in FH deficient cancer cells." (PMID 38374146, 2024). "Metabolites or enzymes of the TCA cycle, such as fumarate hydratase (FH), isocitrate dehydrogenase, succinate dehydrogenase, and α-ketoglutarate dehydrogenase, are known to mutate or be deregulated in human cancers." (PMID 38791507, 2024). "As a key metabolic enzyme in the TCA cycle, FH loss caused by mutation or transcriptional inhibition is related to the occurrence of a variety of cancers." (PMID 38398104, 2024). "On the other hand, individual B carries a FH c.580G > A mutation, which has been implicated in hereditary cancer predisposition." (PMID 39741510, 2024). "Two of them also belong to the set of cancer mutated genes, fumarate hydratase (FH) and 5′-nucleotidase, cytosolic II (NT5C2)." (PMID 36880517, 2023). "Protein alterations similarly described in other malignancies include reduced levels of CD59 in AML35 and cancer-promoting loss of fumarate hydratase (FH) in a variety of cancers." (PMID 37828014, 2023). "A causal relationship between metabolic rewiring and EMT induction has been mostly explored in cancers with genetic deficiencies in metabolic enzymes such as fumarate hydratase (FH), isocitrate dehydrogenase (IDH), and succinate dehydrogenase (SDH)." (PMID 36551699, 2022). "Another key TCA cycle enzyme, fumarate hydratase, whose mutation can cause cancer or a neurological phenotype, is known to be present in two pools, one in the mitochondria and one in the cytosol." (PMID 35563430, 2022). "Over the past twenty years, several mechanisms have been proposed to address the FH role in cancer, mainly focusing on accumulated fumarate due to enzyme loss." (PMID 36428601, 2022). "Some of these mutations (e.g., isocitrate dehydrogenase (IDH), Succinate dehydrogenase (SDH), fumarate hydratase (FH)) lead to the abnormal production of metabolites associated with cancer progression, called “oncometabolites”." (PMID 35869047, 2022). "When mutated/inactivated, FH can cause various diseases, including hereditary and sporadic forms of cancer." (PMID 36139533, 2022). "By univariate survival analysis, we found that FH expression was associated with patients' OS in 8 cancer types, including ACC, KICH, KIRC, KIRP, LAML, LGG, LUAD, and SKCM." (PMID 34737838, 2021).
cancer (continued). "Respiration incompetency plays a natural and critical role in the tumorigenesis of many malignancies, including cancers caused by FH and SDH mutations, cancers harboring pathogenic mitochondrial DNA mutations, or cancers residing in hypoxic environments." (PMID 34827664, 2021). "FH deficiency also protects cancer cells from drugs targeting mitochondrial ETC and causing a metabolic catastrophe, as demonstrated in FH-deficient UOK262 cells treated with ONC201, an anti-GBM agent that decreases OXPHOS-mediated production of ATP." (PMID 34065551, 2021). "One such case is the cancer cells deficient in fumarate hydratase (FH), where the accumulation of fumarate results in conjugation with glutathione to produce succinate glutathione." (PMID 34829708, 2021). "IDH-driven cancers have a prominent CpG island hypermethylation similar to the hypermethylation phenotype seen on SDH- and FH-deficient cancers." (PMID 34201149, 2021). "Using the cBioPortal database, we identified genomic alterations of FH in 32 cancers, including mutations and copy number variations." (PMID 34737838, 2021). "A high expression level of FH was associated with poor prognosis in several types of cancers, particularly in LUAD." (PMID 34737838, 2021). "Particularly, FH-deficient cancer cells undergo a Warburg metabolic shift characterized by aerobic glycolysis and reduced oxidative phosphorylation." (PMID 32751108, 2020). "Some enzymes involved in the TCA cycle are mutated or dysfunctional in different cancers, i.e. fumarate hydratase (FH), succinate dehydrogenase (SDH), and isocitrate dehydrogenase (IDH)." (PMID 31822964, 2020). "In fact, cancer cells deficient for the mitochondrial tumour suppressor fumarate hydratase (FH), a metabolic enzyme of the TCA cycle, were unable to undergo ferroptosis upon cystine deprivation." (PMID 31936571, 2020). "Strikingly, the accumulation of fumarate in FH-deficient cancer cell lines leads to the formation of a peculiar molecule between fumarate and glutathione (GSH), which depletes intracellular NADPH and enhances oxidative stress." (PMID 32266157, 2020). "Loss of FH function, as found in some cancers, results in the accumulation of fumarate and a corresponding decrease in NADH generation." (PMID 31319896, 2019). "The acetylation-impacting genes, IDH2, SDHA/B/C, and FH, are annotated as being frequently mutated in cancers in the COSMIC database." (PMID 30823893, 2019). "Such metabolites have been found to have causative influence in cancers with genetic deficiencies in associated enzymes, including fumarate hydratase (FH), isocitrate dehydrogenase 1 (IDH1), and succinate dehydrogenase (SDH)." (PMID 31164982, 2019). "In summary, this work provides for the first time a genome-scale study of the regulatory implications of post-translational modifications in the metabolism of FH-deficient cancer cells." (PMID 29191787, 2018). "Fumarase also functions as a tumor suppressor, where certain germline loss-of-function mutations in FH predispose individuals to a variety of tumors and cancers." (PMID 29456767, 2018). "In cancer cells with FH mutations, the accumulation of fumarate results in elevated levels of succinic-glutathione (GSF), which acts as an alternative substrate for GSH reductase, ultimately leading to decreased levels of NADPH and GSH." (PMID 28748451, 2018). "It is currently unclear as to how many processes are affected by succination in FH-deficient cancers but an investigation into the potential role of succination in DNA damage checkpoint signalling would be worth exploring." (PMID 30190474, 2018). "A particularly well-studied metabolic alteration in cancer is driven by mutations of the metabolic enzyme fumarate hydratase (FH)." (PMID 29191787, 2018).